INS (insulin)
Diseases named in the same sentence as INS in open-access papers (continued):
Sharing a sentence is not in itself a finding about the gene and the disease.
metabolic syndrome (continued). "Surplus metabolic syndrome subjects defined by IDF, NCEP or ACE definition had higher BMI, waist circumference, SBP, DBP; glucose, insulin, HOMA-IR, TC, and TG values and lower HDL-C values than subjects without the metabolic syndrome." (PMID 18088443, 2007). "Additionally, Mang lowered blood glucose levels in KK-y mice and reversed the elevated plasma insulin and fasting plasma non-esterified fatty acid concentrations during an OGTT test in a rat model of fructose-induced metabolic syndrome." (PMID 40406487, 2025). "The “modern” Western diet and lifestyle, by exerting negative (i.e., stimulating) effects on the activity of the insulin–IGF-I system, may play an important etiological role in the pathogenesis of the metabolic syndrome." (PMID 36901984, 2023). "These pathologies ultimately culminate in metabolic syndrome (MetS), represented as multiple noncommunicable diseases, principally abdominal or central obesity, chronically raised blood pressure, dyslipidemia, IR/impaired insulin glucose metabolism, and steatohepatitis." (PMID 36105908, 2022). "In agreement with this, the meta-analysis on nine RCTs found that consuming curcumin improves dyslipidemia, specifically reducing serum total cholesterol (TC) and LDL-C, ALT, AST, FPG, HOMA-IR, serum insulin, and WC, but not in serum TG, HDL-C, hemoglobin A1c (HbA1c), body weight, and BMI." (PMID 35956400, 2022). "For example, the beneficial role of n3 PUFAs has been postulated for the prevention of metabolic syndrome or T2DM, but there is no conclusive evidence, and some studies have shown a lack of significant effect of n3 PUFA on glycemic control or insulin sensitivity." (PMID 34609622, 2022). "Other markers of metabolic syndrome, including reduced HDL cholesterol, elevated LDL cholesterol, elevated serum glucose, elevated serum non-esterified fatty acid (NEFA), and elevated serum insulin, were also evident in obese animals." (PMID 28746409, 2017). "Although it has been demonstrated that dyslipidemia plays a negative role in β cells functions of non-diabetic individuals, the concrete effects of different lipid profiles (TG, TC, HDL-C and LDL-C) on insulin sensitivity and β cell function are still unclear." (PMID 28199386, 2017). "Baseline BMI, WHR, SBP, diastolic blood pressure (DBP), 2 h-PG, 2 h-insulin, TG, total cholesterol (TC), HOMA-IR were significantly higher and HDL cholesterol was significantly lower in men and women who developed metabolic syndrome compared with those who did not." (PMID 24647445, 2014). "Although evidence for the role of p38 MAPK in metabolic syndrome is still lacking (except for some animal studies in diabetic fibrotic cardiomyopathy), enhanced MAPK signaling was shown to increase both insulin sensitivity and promote hypertrophic cardiac remodeling." (PMID 23365487, 2013). "The HIV-1+ subjects in this cohort had significantly (p<0.05) higher presence of metabolic syndrome, higher levels of total cholesterol, triglycerides and non-HDL cholesterol and insulin levels, serum sCD14 and similar levels of serum LPS compared to the control subjects." (PMID 23510548, 2013). "Adolescents with metabolic syndrome were older, had worse anthropometric parameters, higher systolic and diastolic blood pressure, higher plasma cholesterol, triglyceride, uric acid, gamma-GT, ALT, insulin, and HOMA-IR, and lower HDL-c levels than those who did not." (PMID 37396186, 2023).
Hyperinsulinemia (4,222 papers, 2002 to 2026). An increased concentration of insulin in the blood. "Insulin therapy should adhere to the principles of precision and moderation, avoiding potential tumor-promoting risks associated with hyperinsulinemia, while also noting the inhibitory effects of insulin on cellular autophagy." (PMID 41601937, 2026). "This phenomenon is associated with compensatory hyperinsulinemia, in which insulin signaling through the IRS-1/PI3K/Akt pathway is impaired in muscle, liver, and adipose tissue, which favors lipid accumulation and peripheral lipotoxicity." (PMID 41471698, 2025). "The insulin phenotype, hyperandrogenism, resistance, and hyperinsulinemia are all brought on by mutations in the insulin receptor gene." (PMID 41370421, 2025). "MiR-93, on the other hand, regulates insulin signaling and has been associated with hyperinsulinemia and abnormal glucose metabolism in PCOS patients." (PMID 40497963, 2025). "Managing this requires not only careful insulin adjustment but also monitoring the long-term risk of hyperinsulinemia, which can exacerbate cardiovascular complications and contribute to weight gain." (PMID 39842720, 2025). "When IR results in hyperinsulinemia, it is often associated with a diagnosis of impaired myocardial insulin signaling, mitochondrial dysfunction, and endoplasmic reticulum stress." (PMID 40881124, 2025). "In the pancreas, PPARβ/δ controls β-cell mass and insulin secretion; its deficiency leads to islet hyperplasia and hyperinsulinemia." (PMID 41438090, 2025). "This drives an additional production of insulin by the pancreas, causing hyperinsulinemia that will worsen the resistance and start a vicious cycle." (PMID 40725728, 2025). "The TyG index, as a surrogate marker of IR, reflects underlying metabolic dysregulation, including impaired insulin signaling in target tissues and compensatory hyperinsulinemia, which are key drivers of adverse outcomes in critically ill patients." (PMID 40265186, 2025). "IR, prevalent in this population, causes hyperinsulinemia, disrupting insulin signaling and glucose uptake in the endometrium, which reduces receptivity to embryo implantation." (PMID 40802395, 2025). "IR leads to neural and cognitive abnormalities in the brain, predisposing it to cognitive dysfunction through hyperinsulinemia, impaired insulin signaling, and altered Amyloid Precursor Protein (APP) metabolism." (PMID 39859201, 2025). "Supraphysiologic iatrogenic hyperinsulinemia fosters weight gain, relevant glycaemic excursion, paradoxical increase of hypoglycemic risk, increased food intake, and further insulin requirement." (PMID 40914967, 2025). "Research has demonstrated that the ketogenic diet (KD) can effectively promote weight loss, reduce hyperinsulinemia, and enhance insulin sensitivity." (PMID 41228543, 2025). "High-GI foods cause rapid increases in blood glucose and insulin levels, which can trigger oxidative stress and chronic hyperinsulinemia." (PMID 40474895, 2025). "Systematic reviews and meta‐analyses have quantified the increased CRC risk associated with insulin and TZDs, therapies often linked to weight gain and hyperinsulinemia." (PMID 39980820, 2025). "For instance, insulin therapy has been associated with a RR of 1.69 (95% CI, 1.25–2.27), likely due to hyperinsulinemia‐induced cell proliferation and reduced apoptosis." (PMID 39980820, 2025). "Hyperinsulinemia is linked to lower albumin, albumin/globulin ratio, catalase activity, glucose, and glucose/insulin ratio." (PMID 40901060, 2025). "Hyperinsulinemia is treated only if its cause is an insulinoma, which is a rare tumor of the pancreas that releases excess insulin, causing very symptomatic episodes of hypoglycemia." (PMID 41463109, 2025). "For instance, mutations in the insulin gene (INS) have been shown to cause hyperinsulinemia, hyperproinsulinemia, neonatal diabetes mellitus, MODY10, and autoantibody-negative type 1 diabetes mellitus (DM1)." (PMID 39859454, 2025).
Hyperinsulinemia (continued). "In contrast, fasting insulin directly reflects compensatory hyperinsulinemia caused by impaired muscle insulin action." (PMID 41464556, 2025). "IL-6 can promote the production and secretion of insulin in prediabetes, leading to the occurrence of hyperinsulinemia, which is associated with TNF- α." (PMID 41098781, 2025). "The increase of insulin or hyperinsulinemia more than 20 mU/L was associated with laminitis and Cushing’s disease in ponies and horses." (PMID 40901060, 2025). "In this study, in utero exposure to maternal hyperinsulinemia was associated with altered hypothalamic gene expression and progression to insulin and leptin resistance favoring juvenile obesity." (PMID 39998445, 2025). "Insulinoma is a rare pancreatic neuroendocrine tumor that causes pancreatic beta cells to over‐secrete insulin, leading to hyperinsulinemia due to the loss of normal physiological feedback mechanisms." (PMID 40550558, 2025). "Hyperinsulinemia can be caused by increased pancreatic insulin secretion in the fasting state or postprandially after ingestion of carbohydrates and/or free fatty acids." (PMID 41009753, 2025). "Ovarian tissue remains sensitive to insulin even in the presence of hyperinsulinemia associated with IR." (PMID 40565766, 2025). "IR impairs glucose uptake by the cells of tissues and its catabolism, resulting in a compensatory increase in insulin production from hyper-responsive pancreatic islet β-cell causing the state of hyperinsulinemia." (PMID 41473239, 2025). "The ob-genotype associated extreme hyperinsulinemia was completely reversed by V7-LEP treatment with a 27-fold reduction in serum insulin level compared to V7-GFP mice." (PMID 40709262, 2025). "Insulinoma, a rare pancreatic neuroendocrine tumor, causes pancreatic beta cells to over‐secrete insulin, disrupting the normal physiological feedback mechanism and leading to hyperinsulinemia." (PMID 40550558, 2025). "Hyperinsulinism, characterized by elevated circulating insulin levels, has been implicated in several mechanisms contributing to migraine onset and chronicity." (PMID 40426647, 2025). "We recommend checking for anti-insulin antibodies in cases of endogenous hyperinsulinism associated with an autoimmune disease, despite the absence of any drug treatment." (PMID 40584814, 2025). "Glucokinase is essential for glucose sensing in pancreatic β-cells and for hepatic glycogen synthesis, and a dysregulation of this enzyme has been associated with congenital hyperinsulinism and altered insulin secretion dynamics." (PMID 40606827, 2025). "It is suggested that increased levels of insulin and hyperinsulinemia are associated with the development of a number of cancers, such as colorectal, ovarian, breast and pancreatic cancer." (PMID 38397072, 2024). "Conclusive evidence suggests that insulin induces water and sodium retention and that both endogenous and exogenous hyperinsulinemia are associated with increased blood pressure." (PMID 38841306, 2024). "In this study, we aimed to demonstrate the effects of TRE on the pathogenic changes associated with MASH, including glucose and insulin sensitivity and hyperinsulinemia, and, more importantly, on liver tumor growth in two models of MASH-driven HCC." (PMID 38672595, 2024). "Tumorigenesis can be caused by the hallmark of IR, hyperinsulinemia, and the role of the insulin/insulin-like growth factor system associated with it." (PMID 38572476, 2024). "Hyperinsulinemia occurs because of genetic predisposition, sustained overnutrition, the consumption of a Western diet, and reduced hepatic insulin clearance." (PMID 39769002, 2024). "IR is the decrease in the efficiency of insulin to stimulate the uptake and use of glucose, and the body responds by overproducing insulin, causing hyperinsulinemia, to maintain stable blood glucose levels." (PMID 39346096, 2024).
Hyperinsulinemia (continued). "Adrenal cortisol and noradrenaline response can elevate the blood glucose level above normal values, causing another reactive insulin response and periodic hypo- and hyperglycemic events with recurring hyperinsulinemia." (PMID 38337532, 2024). "Hyperinsulinemia is potentially problematic as it has been shown to directly cause laminitis, and there is an association between increased basal insulin concentrations and increased lameness (pain) due to laminitis." (PMID 38473112, 2024). "On the contrary, the role of insulin is disputed, with some studies concluding a protective role, whereas cerebral hyperinsulinemia is considered a risk factor for CI due to T2DM, which probably contributes to the diabetic model or various other standpoints." (PMID 39767690, 2024). "An animal study revealed that mice with an apelin deficiency had decreased insulin sensitivity and hyperinsulinemia accompanied by reduced adiponectin levels." (PMID 39457235, 2024). "Defective insulin clearance has been linked to T2D as well as hyperinsulinemia-driven systemic insulin resistance and hyperinsulinemia in metabolic syndrome." (PMID 38767782, 2024). "In people with T1DM, during EXE, insulin levels cannot be immediately reduced, which can cause hyperinsulinemia." (PMID 38542818, 2024). "Bergman postulated that (inherited) reduced hepatic insulin clearance causes hyperinsulinemia in the peripheral circulation." (PMID 39769002, 2024). "IR-autoantibodies can cause hyperinsulinemia by 2 mechanisms: inhibiting insulin clearanceand indirectly promoting insulin secretion." (PMID 38304010, 2024). "When compared to normal physiology, insulin absorbed via subcutaneous depots causes hepatic hypoinsulinemia and relative peripheral hyperinsulinemia." (PMID 39768947, 2024). "Another perspective suggests initial Aβ buildup causing neuronal insulin resistance, followed by secondary hyperinsulinemia, exacerbating AD progression." (PMID 38534454, 2024). "INS (preproinsulin gene) mutations, which cause hyperinsulinemia by promoting the production of structurally defective insulin, have been linked to T1DM and T2DM, and neonatal diabetes other than MODY10." (PMID 39201476, 2024). "This adrenal hormone spike has been found to induce resistance to insulin hormone and favor hyperinsulinemia, thereby causing peaks in concentrations of plasma cholesterol and blood glucose." (PMID 39101102, 2024). "The ketogenic diet (KD) has demonstrated efficacy in promoting weight loss, diminishing hyperinsulinemia, and enhancing insulin sensitivity." (PMID 38321127, 2024). "Insulin’s effects on ENaC regulation in the lung and renal epithelium have been described, and hyperinsulinemia is associated with reduction of Na+/K+-ATPase activity in rodents and humans." (PMID 38172968, 2024). "A period of weight loss does not provide lasting benefits after weight regain, and weight cycling is detrimental and associated with hyperinsulinemia and elevated basal insulin secretion." (PMID 38961153, 2024). "Other conventional anti-diabetic drugs have also been scrutinized, with evidence linking hyperinsulinemia to cancer risk, raising concerns about insulin therapy’s carcinogenic potential, though the data remain ambiguous." (PMID 39595655, 2024). "IR causes increased insulin synthesis in β-cells, resulting in hyperinsulinemia as a compensatory response." (PMID 38392069, 2024). "Hyperinsulinemia has been associated with increased tumour risk and progression due to the mitogen effect of insulin." (PMID 39408212, 2024). "Long-term consumption of a high-glycemic/high-insulinogenic WD can cause ß-cell hyperplasia, insulin hypersecretion, hyperinsulinemia, OxS and mitochondrial dysfunction, and eventually the development of IR." (PMID 39012663, 2024). "Termed “peripheral hyperinsulinemia,” elevated levels of systemic insulin have been implicated in the development of IR in this population." (PMID 38435452, 2024).
Hyperinsulinemia (continued). "Secondly, WC animals were found to be predisposed to hyperinsulinemia and elevated basal insulin secretion following re-exposure to WD." (PMID 38961153, 2024). "TA absorption causes metabolic derangements, most notably a marked hyperinsulinemia that is more severe in horses with elevated baseline insulin values." (PMID 38828366, 2024). "Animal experiments have shown that TZD drugs indirectly regulate the expression of UAT and URAT1 mRNA by improving IR and reducing blood insulin levels, thereby reducing hyperuricemia caused by hyperinsulinemia." (PMID 38579756, 2024). "Dapagliflozin, a pharmacological agent known for its capacity to diminish hyperinsulinemia while promoting weight loss, has demonstrated the ability to augment insulin clearance, consequently leading to a further decline in systemic insulin concentrations." (PMID 38735956, 2024). "Endogenous hyperinsulinemia is caused by decreased hepatic clearance and compensatory increased insulin secretion." (PMID 38392069, 2024). "Congenital hyperinsulinism is a common cause of persistent hypoglycaemia in newborns and infants, characterised by an abnormal secretion of insulin by the pancreatic beta-cells." (PMID 38952388, 2024). "The underlying mechanisms of hyperinsulinemia were revealed by measuring insulin antibodies (IAs) and analyzing changes in FINS levels before and after polyethylene glycol (PEG) precipitation." (PMID 37324170, 2023). "Glutamate dehydrogenase, located in the mitochondria of cells, can catalyze the conversion of glutamate into α-ketoglutaric acid and NH4+, regulate amino acid-induced insulin secretion, and induce hyperinsulinemia after mutation." (PMID 36766794, 2023). "Previous gene knockout studies confirmed a role for IDE in insulin clearance; Ide loss-of-function produced hyperinsulinemia and age-dependent glucose-intolerance." (PMID 38077066, 2023). "The role for hyperinsulinemia as a driving factor in this process is poorly understood, though previous work has implicated insulin as a global driver of VAT inflammation." (PMID 36992811, 2023). "Due to the plethora of metabolic derangements caused by hyperinsulinemia, researchers believe that insulin signaling plays a potentially decisive role in tumors, including PDAC59." (PMID 36697410, 2023). "Hyperinsulinemia is also associated with ovarian and adrenal hyperandrogenism, as insulin can stimulate androgen production in the ovaries and adrenal glands." (PMID 37510690, 2023). "Resistance to insulin-stimulated glucose uptake is linked to hyperinsulinemia, glucose intolerance, hypertension, low HDL-cholesterol, and high triglycerides levels while also being able to influence coronary artery disease." (PMID 36677012, 2023). "To better understand the physiology of hyperinsulinemia and ultimately T2D, we implemented a genetic approach grouping fasting insulin (FI)-associated genetic variants based on their molecular and phenotypic similarities." (PMID 37790568, 2023). "IR is a characteristic metabolic disorder that coexists with hyperinsulinemia, long-term exposure of brain neurons to elevated insulin levels also causes neurodegeneration and permanent memory impairment." (PMID 37932783, 2023). "The mechanism of insulin action on the ovaries causes hyperinsulinemia, which causes excessive androgen synthesis and peripheral conversion of androgens to estrogens in adipose tissue, resulting in menstrual cycle disruptions and lower conception rates." (PMID 38021970, 2023). "Previous studies have found a positive correlation between insulin levels and breast cancer risk in postmenopausal women, suggesting that hyperinsulinemia is an independent risk factor for breast cancer." (PMID 37524743, 2023). "Studies have shown that blocking the cannabinoid 1 (CB1) receptor leads to fat loss, reverses the overproduction of leptin and insulin, and has a protective effect on hyperinsulinemia and beta cell dysfunction." (PMID 36600288, 2023).